INS (insulin)
Diseases named in the same sentence as INS in open-access papers (continued):
Sharing a sentence is not in itself a finding about the gene and the disease.
diabetes (continued). "PON1 was also shown to protect from diabetes development in mice, and PON2 was shown to affect hepatic insulin signaling and protected macrophages from high glucose-induced oxidative stress and triglyceride accumulation." (PMID 26779262, 2015). "High dose progesterone treatment accelerated the progression of diabetes in female obese diabetic-prone db/db mice and treatment with RU486 increased insulin and reduced blood glucose levels in both wild-type and db/db mice." (PMID 25866757, 2015). "Diabetes mellitus (DM) is one of the most common metabolic diseases and is divided according to the mechanism in which the hyperglycemia is generated into two types, dysfunction in insulin secretion and resistance to its activity." (PMID 25878713, 2015). "DPP-IV inhibitors have been recently developed as a new class of drugs for the treatment of diabetes, because DPP-IV inhibits glucose metabolism by degrading incretin hormones that play an important role in insulin secretion." (PMID 25793188, 2015). "Currently, for type-1 diabetes mellitus (T1DM), multiple daily insulin (MDI) injections is the most popular treatment throughout the world." (PMID 26498972, 2015). "It is true that diabetes per se may increase the risk of breast cancer, disregarding the use of insulin, as observed in a recent Danish study, suggesting a possible link through some underlying features of diabetes and not through exogenous insulin administration." (PMID 26537234, 2015). "Positive history of diabetes mellitus in a first-degree relative and multiple abnormal values in the OGTT were strongly found to predict the need for insulin management in women with GDM." (PMID 25977899, 2015). "Type 1 diabetes mellitus (T1DM) is an autoimmune disorder that leads to beta cell destruction and lowered insulin production." (PMID 26576437, 2015). "Diabetes mellitus (DM) is a chronic metabolic disorder characterized by hyperglycemia which may be due to unusual discharge of insulin and/or resistance to insulin." (PMID 25591455, 2015). "Despite considerable advances in insulin delivery and glucose monitoring technology, self-monitored blood glucose (SMBG) remains a vital component of modern type 1 diabetes mellitus (T1DM) management." (PMID 27274982, 2015). "Thus, insulin independence may be a predictor of better diabetes remission." (PMID 25103403, 2015). "There is some overlap between the diabetes convention 3A and the T2DM-CT for patients on two insulin injections per day." (PMID 26171143, 2015). "Type 1 diabetes mellitus (T1DM) is an autoimmune disease leading to beta cell destruction and lowered insulin production." (PMID 26576437, 2015). "Thus, a better understanding of the role of the autonomic nervous system in regulating hepatic glucose levels by the central actions of insulin might help to uncover new pharmacological and potentially nonpharmacological therapies to treat diseases such as hypertension and diabetes." (PMID 25948821, 2015). "In addition to the direct disturbances in the insulin signaling of STZ-diabetic rats, the worsening in the insulin responsiveness observed with the progression of the diabetes may be also related to changes in the content of glucose transporters in skeletal muscles." (PMID 26064170, 2015). "Diabetes mellitus (DM) is a syndrome which insulin function or secretion or both impaired." (PMID 26543722, 2015). "Hence, our findings emphasize the likelihood of insulin resistance to be causally related to obstructive rather than restrictive respiratory patterns while supporting the statement that pre-diabetes and abdominal obesity rather than diabetes are causally related to a restrictive respiratory pattern." (PMID 26542243, 2015). "We further demonstrated that diabetes impairs the trafficking of both GLUT-4 and -8, which was rescued by insulin stimulation in the diabetic atria." (PMID 26720696, 2015).
diabetes (continued). "Korean red ginseng powder reduced insulin and C-peptide during oral glucose tolerance tests (OGTT) in patients with mild diabetes." (PMID 28930204, 2015). "Plasma FFA level is elevated in obesity and diabetes in both humans and animals, and lowering FFA leads to increased insulin sensitivity." (PMID 25816341, 2015). "On the other hand, for patients with type 2 diabetes mellitus, basal supported oral therapy (BOT), consisting of basal insulin injection and an oral hypoglycemic agent, is widely used." (PMID 26819737, 2015). "Diabetes Mellitus (DM) is a group of metabolic diseases characterized by hyperglycemia, dyslipidemia, and abnormal protein metabolism that result from defects in both insulin secretion and/or insulin action." (PMID 25887591, 2015). "Type 2 diabetes mellitus (DM) is a metabolic disease characterized by hyperglycemia, a condition which could either be attributed to insufficient insulin secretion or insulin resistance." (PMID 26649063, 2015). "Type 2 diabetes mellitus (T2DM) is a complex polygenic disorder characterized by impaired insulin resistance, insulin secretion, and dysregulation of lipid and protein metabolism with environmental and genetic factors." (PMID 26451383, 2015). "Other underlying factors associated with poor management of diabetes patients was lack of diabetes screening programs, shortages of endocrinologists in more remote regions of Armenia and high social stigma associated with diabetes and insulin-use, especially among younger diabetes patients." (PMID 25925666, 2015). "Type 2 diabetes mellitus (T2DM) is a complex metabolic disorder characterized by sustained hyperglycemia that results from defects in insulin secretion, insulin action or a combination of both." (PMID 26633471, 2015). "Moreover, with the high rates of adverse effects and the potential for prolonged length of stay due to ineffective insulin management by staff, if patient-managed insulin could prove to be more effective, it might reduce the cost of hospital care for diabetes patients." (PMID 26429339, 2015). "Diabetes specific characteristics: HbA1c: hemoglobin A1c; c-peptide: connecting peptide; CarbF: carbohydrate factor; TDD: total daily dose of insulin." (PMID 26317981, 2015). "The present study shows that the stimulated insulin secretion capacity in LADA is intermediate between that of types 1 and 2 diabetes." (PMID 25572256, 2015). "The findings that only 40–50% of patients with diabetes see a remission in diabetes after RYGB, and of those 10% see a reoccurrence each year despite an improvement in insulin secretion and insulin receptor concentration, suggest that this does not occur." (PMID 25876175, 2015). "However, significant correlations were seen between intestinal and femoral muscle GU after surgery, which may indicate that intestinal insulin sensitivity helps promote the resolution of diabetes in an indirect fashion (i.e. via the improvement in whole-body GU)." (PMID 25631620, 2015). "Patients with NAFLD and incident diabetes had higher HOMA-IR values and higher fasting glucose, insulin, HbA1c, MCP-1 and MDA levels than patients with NAFLD alone and control subjects." (PMID 25961500, 2015). "Further on, the diabetes convention also resulted in most diabetes patients on insulin being treated in secondary care, while many of those patients (especially those who need 2 doses of insulin a day) could be cared in primary care with the pivotal role of the GP." (PMID 26171143, 2015). "The purpose of the present study was to evaluate whether human insulin use without confounding exposure to insulin analogs would increase the risk of breast cancer in female patients with type 2 diabetes mellitus, by using the National Health Insurance (NHI) databases of Taiwan." (PMID 26537234, 2015). "From the perspective of the Global Diabetes Advocate, some of the IIF’s positions on access to insulin were detrimental." (PMID 26427953, 2015).
diabetes (continued). "The natural course of type 2 diabetes mellitus (T2DM) is characterized by chronic hyperglycemia, insulin abnormalities, and progressive β-cell dysfunction." (PMID 26262991, 2015). "Nrf2 activators protected against renal damage in streptozotocin-induced diabetes and activated the PKB signaling pathway to improve insulin sensitivity." (PMID 25884658, 2015). "Diabetes mellitus (DM) is a metabolic disorder caused by a lack of insulin and/or pancreatic dysfunction characterized by hyperglycemia." (PMID 25994182, 2015). "In turn, ROSs produced by oxidative stress and mitochondrial dysfunction as well as pro-inflammatory cytokines secreted during inflammation exacerbate insulin/IGF resistance, which is characteristic of both AD and type 2 diabetes mellitus." (PMID 26556341, 2015). "Whereas insulin enhances DAT activity, hypoinsulinemia (produced by experimentally induced diabetes, insulin resistance, or fasting) reduces DAT activity." (PMID 25805560, 2015). "The most efficient early treatment was INS + MEL; it preserved the structure of the rhythm for 5 days before the effects of diabetes were established." (PMID 25960780, 2015). "The present study shows that the magnitude of stimulated insulin secretion in LADA is intermediate between that of type 1 and type 2 diabetes mellitus." (PMID 25572256, 2015). "We employed the HFHS diet-induced hyperinsulinemia, hyperleptinemia, and diabetes rat model to delineate a temporal relationship between the development of NAFLD and the onset of insulin/leptin resistance." (PMID 25658428, 2015). "Current guidelines recommend that insulin treatment should be initiated as early as possible in patients with Type 2 diabetes mellitus (DM) who fail to achieve adequate glycemic control on oral drugs only, as early initiation of insulin has been shown to improve outcomes." (PMID 26913243, 2015). "While this compensatory mechanism may alleviate glucose levels in early or prediabetes, persistent insulin resistance and continued exposure of β-cells to excess blood glucose and lipids promote β-cell dysfunction, failure, and ultimately death, culminating in overt diabetes." (PMID 26693205, 2015). "In the multivariable analysis, insulin use (OR2.07; 95%CI[1.18–3.62]), experiencing more frequently hyperglycemic episodes (OR1.30;95%CI[1.14–1.49]) and better diabetes knowledge (OR1.02, 95%CI[1.01–1.03]) do increase the odds of being a persistent user." (PMID 26086272, 2015). "All participants with overt diabetes at the follow – up had GDM in their index pregnancy and 16 of them (84.2%) had been treated with insulin during pregnancy." (PMID 25884665, 2015). "Finally, future in-depth “omic” studies on blood and islet specimen from partially pancreatectomized patients with reversible diabetes secondary to cholestasis may allow the identification of circulating biomarkers and adaptive traits of beta cells ensued by an acute onset of insulin resistance." (PMID 26248027, 2015). "In the 2007–2008 China National Diabetes and Metabolic Disorders Study (DMS), all subjects underwent a standard 75-g oral glucose tolerance test (OGTT) with blood glucose and insulin measurements." (PMID 25664814, 2015). "In the Diabetes Control and Complications Trial (DCCT), T1D patients receiving intensive insulin treatment showed greater weight gain than those with conventional treatment." (PMID 26317989, 2015). "After collinearity testing was used, in this analysis we included as independent variable HOMA-IR, AUC of plasma insulin, AUC of plasma glucose, LDL-chol, HDL-chol, triglycerides, BMI, and WHR (adjusted for age, gender, and presence of diabetes)." (PMID 26089884, 2015). "Furthermore, insulin has direct role in the metabolism of amyloid-β and the effect of abnormal glucose metablosim may lead to the production of AGEs which contribute to the development of diabetes and dementia." (PMID 26193295, 2015).
diabetes (continued). "The U.S. Diabetes Prevention Program (DPP) demonstrated that lifestyle modification (i.e., low-fat diet and increased physical activity) and the insulin sensitizer medication Metformin (MET) reduced the rate of transition from pre-diabetes to T2DM." (PMID 24884495, 2014). "Type 2 diabetes mellitus (T2DM) is a chronic degenerative disease, phenotypically and genetically characterized by insulin resistance (IR) in insulin-target tissues, and impaired insulin secretion from pancreatic β-cells." (PMID 24690233, 2014). "In addition, long-term effects of temporary intensive insulin therapy on diabetes remission (or at least a prolonged normoglycaemia phase) in newly diagnosed diabetic patients may be partially attributed to the anti-inflammatory activity of insulin." (PMID 25167060, 2014). "The effects of serum FGF21 concentrations on diabetes and diabetic retinopathy were assessed by conditional logistic regression analysis, after adjustment for the other parameters (HOMA-IR, insulin, HbA1c, FGF21, and glucose) by matching." (PMID 24895642, 2014). "Beta cells both produce insulin and sense glucose and calibrate the delivery of appropriate amounts of insulin without causing hypoglycemia or permitting hyperglycemia, a remarkable process occurring reliably – and automatically – throughout a lifetime in a person without diabetes." (PMID 26137512, 2014). "The 6 submitted apps were, Diabetes Logger, Diabetes Health Tracker, You + Your Diabetes, T1NDA, Insulin Calc, and cpSlider." (PMID 25654312, 2014). "In type-2 diabetes mellitus (T2DM), the β-cells largely remain, but they fail to release sufficient insulin to maintain normoglycaemia." (PMID 25145789, 2014). "One patient with pre-existing diabetes mellitus had an SAE of worsening diabetes mellitus, which was thought to be related to the study drug and which required insulin therapy." (PMID 23529827, 2014). "But in diabetics, HP is more prevalent and also HP+ diabetics have a greater HOMA-IR score and need higher levels of insulin for glycemic control." (PMID 25405220, 2014). "Nevertheless, recent studies questioned the benefits of strict glycaemic control, especially using insulin, on CVD in patients with established atherosclerosis or longstanding diabetes." (PMID 24607023, 2014). "Nevertheless, in similar populations of people with diabetes in Boston, in a placebo-controlled randomized trial of 87 people, we were able to measure changes in FMD in response to troglitazone, an insulin-sensitizing agent." (PMID 24398072, 2014). "In vivo study showed that insulin treatment not only restored the impaired function and expression of P-GP at BBB by diabetes, but also upregulated expression and function of P-GP at BBB of normal rats." (PMID 25540622, 2014). "The majority (about 90%) of diabetes is of Type 2 (T2DM) or non-insulin-dependent diabetes mellitus (NIDDM), which is the result of deviations in pancreatic β-cells functions, insulin secretions, and insulin insensitivity." (PMID 24516503, 2014). "Diabetes mellitus (DM) is classified as a group of metabolic diseases with a typical clinical state of hyperglycemia (high blood glucose levels), which is an outcome of defective insulin secretion, insulin action, or both." (PMID 25574400, 2014). "The Diabetes Control and Complications Trial (DCCT) randomly assigned 1441 patients with type I diabetes to “intensive” or “conventional” insulin therapy." (PMID 24829796, 2014). "However, age at diabetes onset and insulin-free period was inversely related: The later type 2 diabetes became manifest, the earlier patients needed insulin therapy, where about 13% variability of the insulin-free period is attributed to the age at diabetes onset." (PMID 24580798, 2014). "Type 2 diabetes mellitus (T2DM) is a progressive condition and most people with this condition will eventually require exogenous insulin to maintain haemoglobin A1c within recommended targets." (PMID 24902877, 2014).
diabetes (continued). "Previous studies concluded that untreated children with diabetes show more pronounced alterations of erythrocyte and PMN deformability than insulin-treated diabetic children." (PMID 24672797, 2014). "Type 2 diabetes mellitus leads to endothelial dysfunction of the coronary circulation due to reduced availability of nitric oxide, accumulation of glycation end products in the arterial wall, impaired insulin signalling, inflammation and other still unknown mechanisms." (PMID 24656118, 2014). "Diabetes mellitus (DM) is a metabolic disorder, characterized by hyperglycemia and by disturbances in the metabolism of fat and protein, resulting from defects in insulin secretion and/or insulin action." (PMID 25587557, 2014). "On the other hand, WC was significantly associated with age (p < 0.001), income (p < 0.05), management of diabetes by OHA (p < 0.05) and insulin (p < 0.05)." (PMID 25113234, 2014). "Ageing in turn can pre-dispose to diabetes and impaired glucose tolerance (IGT) through effects on insulin secretion and insulin action." (PMID 25118634, 2014). "Diabetes mellitus (DM) is a disease that results in chronic inflammation and apoptosis in pancreatic islets in patients with either type 1 or 2 DM and is characterized by abnormal insulin secretion." (PMID 24707284, 2014). "In the surgical (90% depancreatized) rat model of diabetes, REG-1 administration improved insulin secretion." (PMID 24587207, 2014). "It is thought that these 17 individuals with IIS with a decrease in HOMA-IR developed type 2 diabetes as a result of their baseline status, especially the high proportion of pre-diabetes, HOMA-IR value, and low insulin secretion." (PMID 25166121, 2014). "Insulin, insulin-like growth factor-1 (IGF-1), and certain hormones play an important role in promoting neoplasia in diabetics." (PMID 25426078, 2014). "These included the AERx® Insulin Diabetes Management System (Novo-Nordisk A/S, Bagsverd, Denmark; and Aradigm Corp., Hayward, CA) and the AIR® Inhaled Insulin System (Eli Lilly and Co., Indianapolis, IN; and Alkermes Inc., Cambridge, MA)." (PMID 25505695, 2014). "Therefore, treatment with an insulin-sensitizing agent, such as metformin may correct several of the primary pathophysiologic abnormalities, including lipid metabolism, endothelial function, and platelet hyperactivity in patients with diabetes mellitus." (PMID 25510597, 2014). "Finally, given that the amount of circulating insulin does not change during the sensitive-resistant cycle and bears exist with relatively low levels of insulin, rigorously testing the idea of lowering insulin levels to treat diabetes and obesity may have evolutionary rationale." (PMID 25553771, 2014). "None of the adolescents indicated taking antidiabetic drugs (other than insulin: ATC-subgroup A10B), making it very unlikely that adolescents with Type 2 being were included in the diabetes group." (PMID 25303963, 2014). "In our study, all subjects had at least 12 months of diabetes duration because the protocol required at least 6 months of OGLD and then, another 6 months of insulin treatment." (PMID 24667573, 2014). "During malaria, diabetics maintained significantly (P < 0.05) higher levels of BMI, FBG, and HbA1c but lower levels of insulin and HOMAB than controls." (PMID 25587486, 2014). "The Diabetes Control and Complications Trial (DCCT) demonstrated that early use of an intensive treatment with insulin can prolong β-cell reserve in affected individuals." (PMID 25332771, 2014). "Numerous investigations in patients with type 1 diabetes mellitus (T1DM) have shown that CSII therapy was more efficacious than MDI therapy, since CSII decreased the dose of insulin required to a greater degree." (PMID 25187822, 2014). "In women who go on develop diabetes 8 years later, IGFBP-1 concentrations are low relative to insulin levels, perhaps due to a novel inhibitor of IGFBP-1." (PMID 26237614, 2014).